MIF (macrophage migration inhibitory factor)
Diseases named in the same sentence as MIF in open-access papers (continued):
Sharing a sentence is not in itself a finding about the gene and the disease.
Arthritis (continued). "Two groups observed independently that in MIF gene-deficient mice or wild-type mice treated with neutralizing antibody against MIF the onset of arthritis was delayed and synovial inflammation was decreased, although the specific role of MIF in tissue destruction is not clear yet." (PMID 16872482, 2006). "Furthermore, the same study demonstrated that adoptive transfer of WT macrophages could restore the sensitivity of MIF KO mice to arthritis development." (PMID 27313578, 2016). "And in an antigen-induced arthritis model, exogenous MIF reverses the inhibitory effect of GC on arthritis inflammation, but does not affect GC-induced inhibition of delayed-type hypersensitivity, which suggests there are differences in the sensitivity of inflammatory processes to MIF." (PMID 22046508, 2010). "Given that MIF regulates the expression of MMPs during pathological inflammatory responses such as arthritis, we investigated the possible involvement of MMP-2 and MMP-9 in T. gondii-induced MIF-mediated ileitis." (PMID 21977228, 2011). "The antagonism or absence of MIF can alleviate arthritis in the animal model of RA, and MIF serum level is positively associated with RA severity." (PMID 32530555, 2020). "Previous studies have shown that arthritis-affected synovial fibroblasts, virus-infected cells, adipose tissues, and endotoxemia-affected macrophages have increased levels of MIF with no significant surge in MIF mRNA expression." (PMID 29247872, 2017). "In addition, MIF inhibitors can inhibit the activation of macrophages and the expression of inflammatory factors, such as NO, TNF-α and IL-6, which can significantly improve arthritis and articular cartilage injury in rats." (PMID 35395782, 2022).
ischemia (25 papers, 2010 to 2025). A hypoperfusion of the BLOOD through an organ or tissue caused by a PATHOLOGIC CONSTRICTION or obstruction of its BLOOD VESSELS, or an absence of BLOOD CIRCULATION. "DNA fragmentation was reduced in MIF-deficient mice and MIF-deficient mice expressing K78Q, suggesting that MIF acetylation attenuates DNA fragmentation in cortical neurons after ischemia." (PMID 35585040, 2022). "MIF is released by the myocardium and infiltrating leukocytes and impacts various aspects of myocardial ischemia and ischemia-reperfusion injury." (PMID 40092999, 2025). "Of note, another recently published study reported that MIF was important for the protective effects of dexmedetomidine treatment in mice with ischemia-reperfusion injury, in which ischemia lasted 60 minutes." (PMID 40092999, 2025). "Macrophage migration inhibitory factor (MIF) is an immune mediator associated with inflammation, which is upregulated after ischemia in brain tissue." (PMID 36797398, 2023). "Studies have shown that MIF inhibitor ISO-1 can reduce ischemia-induced neuron damage and cerebral infarction in rats by reducing blood–brain barrier permeability and enhancing the tightness of brain endothelial cell connections." (PMID 36797398, 2023). "In conclusion, in the rat model of cerebral ischemia–reperfusion, MIF inhibitor ISO-1 can effectively improve the neurological deficit symptoms of ischemia–reperfusion injury and reduce the infarct volume." (PMID 36797398, 2023). "The macrophage migration inhibitory factor (MIF) is a pro-inflammatory cytokine activated in response to ischemia." (PMID 35805977, 2022). "Together, these results indicate that MIF acetylation on K78 protects cortical neurons after ischemia." (PMID 35585040, 2022). "Among the proteins in the cell death pathway, we selected the MIF protein for further study because MIF serves as a nuclease to induce DNA fragmentation and neuronal death in ischemia." (PMID 35585040, 2022). "Disruption of MIF in mice results in an enlarged infarct area when ischemia is modeled using the middle cerebral artery ligation (MCAI) method." (PMID 35585040, 2022). "The confocal images revealed that WT MIF protein localized in both the cytosol and nucleus in cortical neurons after ischemia." (PMID 35585040, 2022). "In contrast, ischemia resulted in significantly reduced expression of Ccl2 revealing the opposite impact of MIF protein stimulation." (PMID 30678084, 2019). "Mimicking the increased MIF levels during MI, we exposed cardiac fibroblasts to simulated ischemia in the presence of MIF, which led to further reduced expression of pro-fibrotic genes." (PMID 30678084, 2019). "While the expression of Mif and proAdm was further increased, the expression of Ccl2 was attenuated from 9.6-fold increased expression after MIF stimulation to 5.6-fold increased expression after ischemia in the presence of MIF." (PMID 30678084, 2019). "For example, MIF is cardioprotective when cardiac ischemia/reperfusion is brief, but when ischemia is prolonged, MIF activates immune cells and increases inflammation." (PMID 27014277, 2016). "The cardioprotection conferred by MIF has been reported in the specific experimental setting of short IRI (usually 15–20 min of ischemia)." (PMID 27335054, 2016). "Previous experimental studies have shown that ischemia triggers cardiac MIF release into the coronary venous effluent and decreases cardiac MIF content." (PMID 24098445, 2013). "In our patients having suffered from total circulatory arrest and hence whole-body ischemia, MIF levels were correlated with call-response intervals that can be considered as a surrogate for ischemia time." (PMID 22506003, 2012). "Importantly, although the majority of studies reported that MIF has protective effects in MI, it has been postulated that the duration of ischemia influences the effects of MIF in MI pathogenesis." (PMID 40092999, 2025).
ischemia (continued). "Finally, we generated MIF K78Q mutant mice to study MIF K78 acetylation in neuroprotection after ischemia." (PMID 35585040, 2022). "MIF protein was localized in the nuclei of cortical neurons in the penumbra region of WT mice; in contrast, MIF K78Q protein was primarily observed in the cytosol of cortical neurons after ischemia, suggesting that acetylation on K78 attenuates MIF translocation into the nucleus after ischemia." (PMID 35585040, 2022). "To determine whether MIF acetylation on K78 is involved in mitigating neuronal death in response to ischemia, we used AAV-shMIF to knock down neuronal MIF expression." (PMID 35585040, 2022). "Inhibition at this site could be problematic in cardiovascular diseases, as MIF/CD74 signaling conveys cardioprotection in early ischemia/reperfusion injury in the heart via activation of the tissue-protective AMP kinase pathway." (PMID 29581527, 2018). "However, while much is discussed about the apparently detrimental aspects of MIF inflammatory activity, it must be remembered that MIF has been shown to be protective in the early stages of ischemia." (PMID 30083544, 2018). "Male C57/BL6 mice were randomly allocated to receive recombinant mouse MIF (rMIF) at physiological (ng/mL) concentrations in a dose–response fashion before or after a protocol of 35 min of ischemia and 2 h of reperfusion in an isolated Langendorff-perfused model with infarct size as endpoint." (PMID 27335054, 2016). "Various studies also describe MIF as a protective factor in MI-ischemia-reperfusion injury." (PMID 26257740, 2015). "Indeed, while MIF depresses myocardial function in a context of systemic inflammation, it exerts protective effects on the heart in circumstances of ischemia-reperfusion injury." (PMID 23536817, 2013). "Interestingly, our data indicate that the magnitude of MIF release is apparently related to the duration and the extent of ischemia." (PMID 22506003, 2012). "Taken together, the evidence suggests that MIF agonism may be a promising therapeutic approach to improve patient outcomes, but conflicting reports warrant further investigation into the effect of MIF signaling at different stages of ischemia and MI." (PMID 40092999, 2025). "When the period of ischemia has been extended to 30 min followed by a longer reperfusion, the IS-limiting effect of MIF has been lost, suggesting that the protection afforded by MIF might be also dependent of the extent of ischemia." (PMID 27335054, 2016). "Furthermore, both CXCL12 and MIF play a protective role in MI-ischemia-reperfusion injury." (PMID 26257740, 2015). "MIF and D-DT appear to exhibit unidirectional or cooperative activity in endotoxemia, some cancers, chronic obstructive pulmonary disease (COPD), and cardiac ischemia/reperfusion injury and heart failure." (PMID 37616250, 2023). "While MIF stimulation itself had no influence on pro-fibrotic gene expression, simulated ischemia in the presence of recombinant MIF revealed a further reduction of pro-fibrotic gene expression compared with ischemia in the absence of MIF." (PMID 30678084, 2019). "While MIF stimulation alone did not change the expression of pro-fibrotic genes in cardiac fibroblasts, ischemia reduced their expression." (PMID 30678084, 2019). "MIF release, also detected by Western blot, followed a similar kinetic as HMGB1 release and was also released significantly higher upon mechanical stress compared to ischemia only." (PMID 21197406, 2010). "Furthermore, MIF K78 acetylation was decreased in the penumbra regions of the cortex 3 days after ischemic stroke, likely resulting from increased HDAC6 expression in the cortex after ischemia." (PMID 35585040, 2022). "The expression of MAP2 was higher in the MCAO+MIF group than in the MCAO+veh group (* p < 0.0001), indicating that neuronal viability may be increased if the MIF were administered even after experiencing ischemia." (PMID 35805977, 2022).
type 2 diabetes (25 papers, 2011 to 2025). "Monocyte chemoattractant protein-1 (MCP-1) and migration inhibitor factor (MIF) are positively associated with obesity; these chemokines have the ability to induce insulin resistance and are predictors for type 2 diabetes." (PMID 24089589, 2013). "These previous reports are in line with our findings that MIF may be a causal factor of left ventricular diastolic dysfunction in patients with type 2 diabetes." (PMID 21283592, 2011). "Importantly, MIF is associated with impaired glucose tolerance in type 2 diabetes." (PMID 21283592, 2011). "Supporting this, both adipose tissue MIF mRNA and circulating MIF concentrations are elevated in obese women with type 2 diabetes." (PMID 41036138, 2025). "Recent research has also revealed a positive correlation between MIF concentration in the lumbar ligamentum flavum and its thickness in patients with type 2 diabetes and spinal stenosis." (PMID 34445689, 2021). "The levels of MIF, insulin, ghrelin, leptin, glucagon, resistin and adipsin are similar in type 2 diabetes and CHD patients whereas IL-1α, IL-2R, IL-12, IL-18, HGF, and PAI-1 are higher in CHD patients than in type 2 diabetes patients (with p-value <0.01)." (PMID 22745767, 2012). "Our findings indicate that hyperglycemia is a causal factor for increased levels of pro-inflammatory cytokine MIF which plays a role in the development of cardiomyopathy occurring in patients with type 2 diabetes." (PMID 21283592, 2011). "The plasma MIF concentrations of patients with type 2 diabetes with LVDD were significantly higher than that of diabetic patients without LVDD (3.39±0.96 vs 2.59±0.59 ng/ml, p<0.05)." (PMID 21283592, 2011). "Macrophage migration inhibitory factor (MIF) is one of the cytokines that has been shown to be increased in patients with type 2 diabetes." (PMID 21283592, 2011). "Moreover, the blood concentration of macrophage migration inhibitory factor (MIF), which is a humoral factor that controls the migration of macrophage, in type 2 diabetic patients has been reported to be higher than that of healthy persons." (PMID 28168013, 2017). "In conclusion, our data suggest that MIF are involved in the pathogenesis of LVDD in patients with type 2 diabetes and GRK2 may play a role in mediating MIF's effect." (PMID 21283592, 2011). "It has been shown that both MIF and CD74 in serum and urine are dramatically elevated in patients with type 2 diabetes and are positively correlated with severe podocyte injury." (PMID 35563296, 2022). "Overall these data highlight that the simultaneous presence of CHC and type 2 diabetes induces an evident increase of the following proinflammatory cytokines: IL-1α, IL-2R, IL-12, IL-18, CXCL9, MIF and HGF." (PMID 22745767, 2012). "The main finding of the present study is an increase in serum MMP-9 and MIF concentrations in healthy nonobese subjects with family history of type 2 diabetes." (PMID 30302090, 2018).
anemia (24 papers, 2009 to 2026). A reduction in the number of red blood cells, the amount of hemoglobin, and/or the volume of packed red blood cells. "Proinflammatory cytokines like interferon (IFN), tumor necrosis factor (TNF), macrophage migration inhibitory factor, and hemozoin have been linked to the pathogenesis of haemolysis and anaemia during malaria infection, according to a number of studies." (PMID 38566916, 2024). "Experimental infections of BALB/c mice with Plasmodium chabaudi chabaudi (P. chabaudi chabaudi), which is a model for SMA, showed that an elevated plasma MIF concentration is associated with severe anaemia and impairment of erythropoiesis." (PMID 35464430, 2022). "Many other proinflammatory cytokines such as IL12, nitric oxide (NO), and migration inhibitory factor (MIF) have been implicated in pathophysiology of anemia." (PMID 27034825, 2016). "Here, we evaluated the role of MIF in T. congolense infection-associated anemia development, by focusing on the modulation of the erythropoietic and erythrophagocytic potential in tissues including the bone marrow, the spleen and the liver." (PMID 27632207, 2016). "It was demonstrate that, in children, hemozoin acquisition by monocytes was associated with low levels of peripheral blood MIF and increased severity of anemia." (PMID 27034825, 2016). "Collectively, these results suggest that the M1-type MYPS cell associated molecules galectin-3 and MIF both promote the most prominent pathological features of experimental trypanosome infections (anemia and liver injury)." (PMID 26090446, 2015). "MIF deficient animals also featured limited anemia, coinciding with increased iron bio-availability, improved erythropoiesis and reduced RBC clearance during the chronic phase of infection." (PMID 25255103, 2014). "In this regard, augmented MIF circulating levels detected in Plasmodium-infected patients have been associated with anemia and lethal cerebral malaria." (PMID 23451183, 2013). "In addition, in the context of African trypanosome infections, MIF was shown to promote the most important immunopathologies linked to the infection, such as anaemia and liver damage." (PMID 35464430, 2022). "Moreover, a thorough investigation using MIF-deficient mice revealed that the underlying mechanisms in AT-associated anemia development in trypanosusceptible and tolerant animals are quite distinct." (PMID 29497418, 2018). "MIF deficiency also limited hepato-splenomegaly and tissue destruction, including anemia." (PMID 27632207, 2016). "Together, this study suggests that interfering with MIF signaling could represent an approach to limit inflammation-associated anemia complications during natural T. congolense trypanosomosis." (PMID 27632207, 2016). "Hereby, MIF-deficient and neutralizing anti-MIF antibody-treated wild type (WT) T. brucei-infected mice exhibited decreased inflammatory responses, reduced liver damage and anemia (i.e. the most prominent pathogenicity features) compared to WT control mice." (PMID 25255103, 2014). "This notion was strengthened by the fact that interfering with MIF signaling using a Nb-based approach indeed attenuates the excessive inflammatory immune response as well as the most prominent pathological feature associated with T. congolense infections, i. e. anemia, in TgAlbCre-IL10-/- mice." (PMID 32012211, 2020). "Therefore, MIF might be an “important” player (upstream regulator) in African trypanosomiasis-associated anemia, mainly during the chronic stage of anemia development by fueling/promoting pathogenic M1 and could be considered as a prime anti-disease target." (PMID 29497418, 2018). "It has been also demonstrated in murine studies that compared to wild-type controls, MIF-knockout mice infected with malaria develop less severe anemia, exhibit improved erythroid progenitor development, and display higher survival rates." (PMID 40980010, 2025).